LINC00533 (long independently transcribed non-coding RNA 533)
Synonyms: bA373N24.1; C6orf39; C6orf38
Gene: Long non-coding RNA gene on chromosome 6 (28,647,356 to 28,710,117, reverse strand). Ensembl gene ENSG00000235570.
Gene Ontology:
Molecular function: triplet codon-amino acid adaptor activity
Biological process: translation